MED12 (mediator complex subunit 12)
Diseases named in the same sentence as MED12 in open-access papers (continued):
Sharing a sentence is not in itself a finding about the gene and the disease.
adenosarcoma (1 paper, 2017). A low grade malignant neoplasm characterized by the presence of a benign epithelial component (tubular and cleft-like glands) and a low grade sarcomatous component that contains varying amounts of fibrous and smooth muscle tissues. "Given that benign PTs display a significantly lower mutation burden than malignant PTs and lack mutations affecting bona fide cancer genes, only MED12 remained significantly more frequently mutated in benign PTs than in adenosarcomas (83% vs 5%; Fisher's exact test, P = 0.0006)." (PMID 28267263, 2017). "PTs significantly more frequently displayed mutations affecting MED12, the TERT gene promoter and bona fide cancer genes, whereas adenosarcomas harbored a higher rate of MDM2/CDK4 and TERT gene amplifications." (PMID 28267263, 2017). "Exon 2 MED12 mutations, which are founder clonal mutations in a large subset of PTs, were not present in adenosarcomas." (PMID 28267263, 2017). "Notably, one adenosarcoma displayed a MED12 mutation, but the latter was not in exon 2, the exon recurrently affected in PTs." (PMID 28267263, 2017).
anaplastic thyroid cancer (1 paper, 2018).
bile duct carcinoma (1 paper, 2025). "Similarly, in humans, Mediator subunits MED12, MED14, MED23, and MED24 interact with YAP in bile duct carcinoma cells." (PMID 39752503, 2025).
bladder tumors (1 paper, 2021). "Indeed, analyses of TCGA datasets of ovarian and bladder tumors indicated that MED12 expression levels can stratify the survival of patients with BRCA2-mutant tumors: low MED12 levels trended towards reduced survival of these patients, while high MED12 levels trended towards increased survival." (PMID 34871431, 2021).
Blepharophimosis (1 paper, 2018). A fixed reduction in the vertical distance between the upper and lower eyelids with short palpebral fissures. "With the exception of KAT6B mutations identified in the SBBYS variant, and MED12 in an X-linked variant of Ohdo, the lack of known molecular causes has so far hampered more definitive classification of this broad group of blepharophimosis-ID syndromes." (PMID 29021403, 2018).
breast fibroepithelial tumors (1 paper, 2016). "The high frequency and similar patterns of MED12 mutations in FAs and various grades of PTs imply that MED12 mutation is a common and early pathological event in breast fibroepithelial tumors." (PMID 27806318, 2016).
conotruncal heart defects (1 paper, 2020). "No other reports about the involvement of MED12 gene in syndromic conotruncal heart defects are actually available from the literature and the international genomic databases." (PMID 32682435, 2020).
craniorachischisis (1 paper, 2021). Craniorachischisis is the most severe form of neural tube defect in which both the brain and spinal cord remain open to varying degrees. "As a result, we validated one heterozygous somatic variant of MED12 c.5344C > T (p.Arg1782Cys) in the lesion site tissue of a terminated female fetus diagnosed with craniorachischisis." (PMID 33748132, 2021). "Furthermore, this mutation was identified in a case with craniorachischisis, and the tissues were obtained from the high spinal region where closure 1 was expected to occur, so we speculate that during development the MED12 mutation may only be present in neural tissue, not non-neural ectoderm." (PMID 33748132, 2021).
diaphragmatic hernia (1 paper, 2025). A congenital or acquired weakness or opening in the diaphragm which allows abdominal contents to protrude into the chest cavity; congenital diaphragmatic hernias are caused when the embryonic diaphragm fails to fuse. "Although this variant was also detected in the initial analysis, the clinical phenotype, including a diaphragmatic hernia, did not align with any previously known MED12‐associated disorders, resulting in suspicion but not a definitive genetic diagnosis." (PMID 40078074, 2025).
female sterility (1 paper, 2026). "Previous research showed that oocyte-specific loss of Med12, an X-linked gene and Mediator complex subunit, leads to female sterility despite normal folliculogenesis and ovulation." (PMID 41874410, 2026).
fibromatosis (1 paper, 2016). A poorly circumscribed neoplasm arising from the soft tissues. "This analysis confirmed a strikingly high frequency of MED12 exon 1 and 2 mutations in 41/83 PTs (49.4%) and 7/10 FAs (70%), but in only 1/11 cases of fibromatosis (9.1%)." (PMID 27806318, 2016). "We studied MED12 exon 1 and 2 mutations in a series of 83 primary PTs (24 benign, 30 borderline and 29 malignant), 10 FAs and 11 cases of fibromatosis." (PMID 27806318, 2016). "The low level of MED12 mutations in fibromatosis indicates that this gene is not a major mutational event in this tumor type." (PMID 27806318, 2016).
fumarate hydratase deficiency (1 paper, 2024). "With regards to pathophysiology, research has identified MED12 mutations, HMGA2 overexpression, fumarate hydratase deficiency, and cytogenetic abnormalities as contributors to the development of UL." (PMID 38790186, 2024).
microphthalmia (1 paper, 2023). Congenital or developmental anomaly in which the eyeballs are abnormally small. "In fetal extremity anomalies, overlapping fingers/clinodactyly with or without clenched hand is remarkable in early (12–13 weeks) gestation screening, which makes it a more favorable indicator than facial deformities such as microphthalmia or microretrognathia in fetuses with MED12 deficiency." (PMID 37501721, 2023).
muscle tumors (1 paper, 2012). "Are MED12 mutations exclusive to human uterine smooth muscle tumors?" (PMID 22768200, 2012).
papillary thyroid cancer (1 paper, 2022). "MED12 expression has been reported to be downregulated in papillary thyroid cancer leading to activation of TGFβ signaling." (PMID 35954227, 2022).
pelvic inflammatory disease (1 paper, 2017). Pelvic inflammatory disease (PID) is an acute or chronic inflammation in the pelvic cavity. "In the analysis of clinical variables, the number of MED12-mutation-positive tumours showed an inverse association with parity, and the number of mutation-negative tumours showed a positive association with a history of pelvic inflammatory disease." (PMID 28432313, 2017).
schwannoma (1 paper, 2020). A benign, usually encapsulated slow growing tumor composed of Schwann cells. "Particularly, ATM, accounting for 33% of the samples, was the most frequently mutated cancer-related gene in schwannoma, followed by CHD4, FAT1, KMT2D, MED12, NF2, and SUFU (>20%)." (PMID 33193598, 2020).
uterine malignant tumors (1 paper, 2012). "Inhibition of MED12 expression seems to be specific to a subgroup of uterine malignant tumors (STUMP and LMS)." (PMID 22768200, 2012).
tumor (121 papers, 2009 to 2026). "Recent studies have highlighted the role of MED12 in tumor initiation, as demonstrated by the development of Lyo-like tumors in transgenic mice with uterine-specific MED12 mutations." (PMID 40004152, 2025). "The identification of identical MED12 p.G44D mutations in both tumor types confirms a shared molecular origin, establishing disruption of the Mediator kinase module as a common vulnerability in hormone-responsive mesenchymal tissues." (PMID 41156195, 2025). "Among them, MZF1, OGT, LHX4, and MED12 have been implicated in tumor stemness, drug resistance, and immune escape mechanisms." (PMID 40963600, 2025). "Analysis confirmed MED12 mutations as a common initiating event in both tumor types, identified in 5/15 (33%) UL and 2/7 (29%) FA samples." (PMID 41156195, 2025). "Critically, both tumor types harbored the identical missense mutation c.131G > A (p.Gly44Asp) in exon 2, a known hotspot that disrupts MED12-Cyclin C binding and impairs CDK8/19 kinase activity within the Mediator transcriptional complex." (PMID 41156195, 2025). "Both tumor types harbored identical MED12 p.G44D mutations, confirming mediator complex dysfunction as a unifying driver in hormone-responsive tissues." (PMID 41156195, 2025). "Trametinib’s ability to inhibit tumor growth in vivo, particularly in the context of MED12 mutations, suggests its potential as a strategy to overcome resistance to RTK inhibitors." (PMID 40833497, 2025). "Second, expression of an orthologous UF-linked Med12 mutant transgene in mice elicits tumor formation, providing direct genetic proof of disease causality." (PMID 39764110, 2024). "Along with their high frequency occurrence, two additional findings suggest that MED12 mutations are tumor drivers." (PMID 39764110, 2024). "Since tumor-associated MED12 mutations lead to full inactivation of protein function, our knockdown system should recapitulate a MED12 mutant setting." (PMID 38915457, 2024). "We have previously reported on the differential expression of protein-coding genes, some of which are influenced by race and MED12 mutation of the tumor." (PMID 38279317, 2024). "This agrees with previous studies that reported two mutation types in MED12 exon 2 (including missense and inframe insertion-deletion mutations) identified in the human tumours." (PMID 37113812, 2023). "The expression of several race-associated genes was also dependent on the MED12 mutation status of the tumor, being higher (FRAT2, TNFRSF19, ACP7, IRS4, PLEKHG4B, KRT17, SLN, and ZNF703) or lower (CAV2) in the mutated specimens compared with wild-type tumors." (PMID 37686244, 2023). "MED12 Gly-44 mutations are causal in inducing higher cell proliferation and, eventually, fibroid tumor formation in humans and mice." (PMID 37429859, 2023). "A UL mouse model demonstrates that the expression of MED12 c.131G>A mutant allele in uterine tissue is sufficient for the development of UL-like tumours with chromosomal aberrations." (PMID 36982825, 2023). "Although UF-linked MED12 mutations are proven tumor drivers, the molecular basis for their tumorigenic activity is nonetheless poorly understood." (PMID 35418189, 2022). "Tumors with MED12 mutations contain almost equal populations of smooth muscle cells and tumor-associated fibroblasts, although casual MED12 mutations are present only in the smooth muscle cells." (PMID 35203298, 2022). "The expression of some of these SE-lncRNAs correlate with race/ethnicity and MED12 mutation status of the tumor." (PMID 35641855, 2022). "Altogether, these observations suggest that MED12 mutations are precursors to chromosomal rearrangements that alter genome integrity and drive tumor progression." (PMID 35418189, 2022).
tumor (continued). "Nonetheless, the underlying mechanism by which MED12 mutations trigger genomic instability and tumor formation remains to be established." (PMID 35418189, 2022). "Mutations in the MED12 gene are prevalent in uterine LM and thus have been implicated in LM tumor development." (PMID 35869560, 2022). "Since the discovery of frequent MED12 mutations in FA and PT, next-generation sequencing has been used to search for other gene mutations in these tumours." (PMID 33046803, 2021). "None of the other variables, such as patients’ age, FA classification, PT grade and MED12-mutation status, differed significantly between TERTpMut+ and TERTpMut− tumours." (PMID 33046803, 2021). "A study into the MED12 status of leimyosarcomata found MED12 exon 2 mutations in only 7% of tumours, which argues against this mutation as the driving force behind the malignancies." (PMID 36304022, 2021). "MED12 mutations for all cases and TERTp mutations for 17 tumours were detected by Sanger sequencing." (PMID 33046803, 2021). "Out of 6 karyotypically abnormal ULs subjected to a comparative analysis of the abnormal clone proportion across paired cultured and uncultured samples, 3 tumours had missense mutations in codon 44 of MED12 exon 2, while the remainders were MED12-negative." (PMID 34944592, 2021). "Since we have used standard media previously used in 2D cultures, our results support the idea that ECM is fundamental for in vitro survival and growth of tumour cells carrying MED12 mutations." (PMID 32251338, 2020). "At the transcriptional level, tumours with MED12 mutation barely respond to E2 stimulation contrary to what was observed in slices from tumour without MED12 mutations." (PMID 32251338, 2020). "We sequenced the exon 2 hot-spot region of MED12 in the 11 UL analyzed and found mutation in 8 tumours." (PMID 32251338, 2020). "According to driver alterations, MED12 was mutated in 4 tumours (MED12mut) while HMGA2 upregulation was detected in tumour L23." (PMID 32251338, 2020). "Hotspot MED12 exon 2 mutations have been shown to contribute to most of these neoplasms, and assays revealed that PTs display higher mutational burdens." (PMID 31862014, 2019). "Mutations in exon 2 of MED12 were identified in 39% (14 of 36) of LM tumor specimens, and the ACLY gene was mutated in 6% (two of 36) of LM tumor specimens." (PMID 32232185, 2019). "MED12-LMs consist of a similar number of MED12-mutant smooth muscle cells (SMCs) and MED12-wild-type tumor-associated fibroblasts (TAFs)." (PMID 30547045, 2018). "The present study proposed a mechanism for disease progression in which combined CTNNB1 missense mutation p.Ser33Phe and MED12 frameshift mutation p.Tyr1278fs promote tumor progression in MPNST." (PMID 29369179, 2018). "An interesting inverse correlation between tumor size and LH is observed when tumor is positive to MED12 mutation (p < 0.05)." (PMID 30619444, 2018). "Even more impressive, in the same study 52 (8.7%)MED12-mutation positive tumors made their appearance as the sole tumor with this mutation, while 547 (91.3%) tumors were associated with at least one other tumor of this genetic subgroup." (PMID 30647905, 2018). "MED12 mutations constitute highly frequent driver mutations in uterine leiomyomas and fibroadenomas, i.e. two tumor entities that occur almost exclusively in middle-aged and young women, respectively." (PMID 30647905, 2018). "In the present study, LH level is negatively correlated with tumor size when MED12 mutation is present." (PMID 30619444, 2018). "These samples underwent screening for MED12-hotspot mutations, after which we tested the association of the mutation status with tumour characteristics and clinical factors." (PMID 28432313, 2017). "It is noteworthy that the single MED12-mutant PT without FA-like areas harbored a subclonal MED12 mutation, indicating intra-tumor heterogeneity, whereas in all the other MED12-mutant cases, the MED12 mutation was clonal and FA-like areas were present." (PMID 29043292, 2017).
tumor (continued). "We were able to identify, however, truncating mutations in RB1 and MED12 that are very likely to be somatic oncogenic drivers in this patient given the well-established role of these two genes as tumor suppressors across multiple tumor types." (PMID 28390395, 2017). "In the analysis of tumour characteristics, positive MED12-mutation status was significantly associated with smaller tumour size, conventional histology, and subserous location, relative to intramural." (PMID 28432313, 2017). "MED12 exon 2 mutations were predicted to be clonal by ABSOLUTE (i.e. present in virtually 100% of tumor cells analyzed in each sample) in all PTs with FA-like areas cases." (PMID 29043292, 2017). "Here, these tumors harbored the lowest number of MED12 mutations of all tumor types analyzed (8.1%, 3/37)." (PMID 28592321, 2017). "As novel findings, the MED12-mutation-positive tumours were associated with subserous type and their number was inversely associated with parity, whereas the number of mutation-negative tumours was associated with a history of PID." (PMID 28432313, 2017). "This temporal heterogeneity also raises the possibility that these tumors are more likely to be new primary lesions rather than recurrences, as it would be unlikely for a new MED12 mutation to emerge in a tumor that already harbors a MED12 mutation." (PMID 27806318, 2016). "It is therefore possible that a chronic reduction in DNA repair capacity eventually causes the emergence of mutations such as Med12 in myometrial stem cells converting them into fibroid tumor-forming stem cells, and thereby leads to the development of UFs." (PMID 26973527, 2016). "UFs likely originate when a Med12 mutation occurs in a myometrial stem cell converting it into a tumor-forming stem cell leading to a clonal fibroid lesion." (PMID 26973527, 2016). "If the current association is causative, MED12 is a tumor suppressor gene, leading to abnormal leiomyomatous growth when mutated." (PMID 22428002, 2012). "The frequency of MED12 exon 2 mutations was analysed in altogether 1158 tumours by direct sequencing." (PMID 23132392, 2012). "Although it is presently unclear how MED12 mutations trigger neoplastic transformation, MED12-mutant UFs are nonetheless characterized by significant chromosomal loss and rearrangement, suggesting genomic instability as a driving force in tumor development." (PMID 41646338, 2026). "MED12 mutations are common and are thought to play a role in tumour initiation." (PMID 38966061, 2024). "ROS is implicated in both promoting MED12 mutations and facilitating tumor growth." (PMID 39640883, 2024). "For FH-negative mutation fibroids (in ULM7.1, ULM7.2, ULM7.3, ULM7.4 and ULM7.8) observed in this patient, the presence of other genetic mutations such as MED12 are still active in the subset of these fibroids, and the MED12 mutation alone can drive tumour formation." (PMID 37113812, 2023). "The findings support previous studies indicating that MED12 mutations or other genetic modifications may activate quiescent myometrium stem cells, which may serve as cellular clones for tumor development and growth." (PMID 37607000, 2023). "Interestingly, one (sample ULM8.3) out of these five tumours with FH mutations also had a missense mutation, affecting codon 44 in exon 2 of MED12." (PMID 37113812, 2023). "In addition to their high-frequency occurrence, the fact that MED12 mutations are predominantly allelically expressed in human UFs initially suggested a causative role in tumor formation." (PMID 35418189, 2022).